EZH2 (enhancer of zeste 2 polycomb repressive complex 2 subunit)
Diseases named in the same sentence as EZH2 in open-access papers (continued):
Sharing a sentence is not in itself a finding about the gene and the disease.
prostate carcinoma (continued). "In summary, we report that Myc can activate EZH2 expression in prostate cancer by 2 distinct mechanisms-via direct transcriptional activation of the EZH2 promoter, as well as via repression of miR-26a and miR-26b, which themselves can repress EZH2." (PMID 21941025, 2011). "For example, it was shown that depletion of EZH2 by RNAi in prostate cancer cells diminished their tumorigenic and metastatic potential in vitro and in an orthotopic model in nude mice." (PMID 21886846, 2011). "Although prior studies in prostate cancer have revealed a number of possible mechanisms of EZH2 upregulation, these changes cannot account for the overexpression EZH2 in many primary prostate cancers, nor in most cases of high grade PIN." (PMID 21941025, 2011). "Since Myc is commonly overexpressed in human PIN and early carcinoma lesions, it is likely that overexpression of Myc is a key driver of EZH2 overexpression during the early phases of prostate cancer formation." (PMID 21941025, 2011). "We prepared crude whole cell lysates from 5 matched benign and primary prostate cancer specimens and verified that EZH2 protein expression was elevated in the tumors." (PMID 21941025, 2011). "In DU145 and PC3 cells that had been depleted of MYC by siRNA-mediated knockdown, we observed reduced EZH2 promoter activity (p<0.02 for both cell lines),indicating that MYC can indeed activate EZH2 transcription in prostate cancer cell lines." (PMID 21941025, 2011). "EZH2 promoter occupancy by ERG was also demonstrated in prostate cancer clinical samples, providing in vivo evidence of this interaction." (PMID 20479932, 2010). "In benign prostate epithelial cells, EZH2 is expressed at low levels in the cytoplasm but becomes overexpressed in prostate cancer cells, in which its putative function is regulation of actin polymerisation." (PMID 20823885, 2010). "PcG proteins, in particular EZH2 has been shown to downregulate E-cadherin in breast and prostate cancer cells." (PMID 20569464, 2010). "miR-101/EZH2 was found to be deregulated in several other types of cancer, including prostate cancer, bladder transitional cell carcinoma, gastric cancer, and described to strongly correlate with migration, invasion, and metastasis." (PMID 21321380, 2010). "In this report, we present our study showing that microRNA-101 (miR-101) inhibits Ezh2 expression and differentially regulates prostate cancer cells." (PMID 20478051, 2010). "EZH2 has been shown to be up-regulated in prostate cancers compared to normal prostate with particularly higher levels in high grade and metastatic tumors." (PMID 20479932, 2010). "MiR-101 negatively regulates Ezh2 expression and concurrently attenuates the invasion ability of prostate cancer cells, which can be rescued by ectopically expressed Ezh2." (PMID 20478051, 2010). "Very recently, H3K27me3 modifications were mapped in both prostate cancer and normal cell lines and a set of genes silenced by EZH2-mediated H3K27 trimethylation specifically in prostate cancer was identified." (PMID 19262738, 2009). "We found that the most significantly changed epigenetic regulators in both prostate cancer tissues and cell lines were EZH2, SMYD3 and DNMT3A, which function as H3K27 trimethyltransferase, H3K4 di/tri-methyltransferase and DNA methyltransferase, respectively." (PMID 19262738, 2009). "Both works shed light on the silencing function of EZH2 in prostate cancer, but little is known about epigenetic gene activation in prostate carcinogenesis." (PMID 19262738, 2009). "The MSMB gene, which encodes the inhibitor of prostate cancer development PSP94, appears to be similarly targeted by EZH2." (PMID 19002169, 2009). "Although the numbers investigated in each group were small, there appeared to be a dominant response to BMI-1 in the patients with colorectal and prostate cancer, whereas stronger reactivity to EZH2 was more common among the HCC patients." (PMID 17024127, 2006).
prostate carcinoma (continued). "The result indicated poorer prognosis with increased EZH2-positive staining and suggests prostate cancer progression and metastasis with increased EZH2 expression." (PMID 16880794, 2006). "Functional EZH2-specific T cells have previously been isolated from patients with prostate cancer using HLA-A2402-restricted peptides." (PMID 17024127, 2006). "Future research should focus on exploring the complex regulatory networks of SETD2 and EZH2 in prostate cancer, refining current inhibitor-based treatment regimens, and enhancing combination treatment strategies to improve therapeutic outcomes and patient quality of life." (PMID 40959108, 2025). "Explore combination strategies that target OCT4 and other key master regulators—such as SOX2, MYC, EZH2, and BRN2—alongside immunotherapies, to more effectively disrupt the stemness and immune-evasive phenotypes associated with lineage plasticity in prostate cancer." (PMID 40722714, 2025). "In prostate cancer cells, testosterone induces the expression of both EZH2 and ATAD2." (PMID 41154392, 2025). "In addition, EZH2-mediated trimethylation of H3K27 is significantly increased in advanced metastatic prostate cancers, which promotes cell proliferation and suppresses tumor suppressor gene expression." (PMID 40760406, 2025). "EZH2 is a well-established oncogene whose overexpression leads to transcriptional silencing of tumor suppressor genes, thereby promoting proliferation, metastasis, and resistance to hormonal therapies in prostate cancer 9-11." (PMID 40959108, 2025). "Together, our data highlight a critical role for EZH2 in maintaining phenotypic plasticity in prostate cancer models involving Rb1 deletion and suggest that its inhibition may restore chromatin dynamics that constrain lineage infidelity." (PMID 40832297, 2025). "Reports from prostate cancer suggest polycomb-independent oncogenic functions of EZH2 that converge on AKT activation, and similar EZH2-mediated mechanisms have been linked to resistance to PARP inhibitors in ovarian cancer and to EGFR inhibitors in lung cancer." (PMID 41156200, 2025). "Furthermore, X2K (eXpression2Kinases) analysis of UP DEGs in AA prostate cancer samples showed enrichment of EZH2 and SUZ12 transcription factors which are elements of PRC2 complex." (PMID 40104216, 2025). "EZH2 usually overexpressed in prostate cancer compared with normal prostate tissue." (PMID 40959108, 2025). "Inhibition of EZH2 can enhance the anti-tumor effect of metformin in prostate cancer." (PMID 40959108, 2025). "USP7 promoted the deubiquitination of EZH2, thereby accelerating prostate cancer cell metastasis." (PMID 40329406, 2025). "Both SETD2 and EZH2 are KMTs, and involved in prostate cancer progression." (PMID 40959108, 2025). "DNMT1 promotes prostate cancer progression and metastasis by enhancing TRAF6 transcription and facilitating TNF receptor-associated factor 6 (TRAF6)-mediated ubiquitination of EZH2, underscoring its pivotal role in tumorigenesis and potential as a therapeutic target." (PMID 40034825, 2025). "EZH2 mediate IFN-γ-JAK-STAT1 signaling pathway inactivation to promote prostate cancer progression." (PMID 40959108, 2025). "EZH2 is commonly overexpressed in prostate cancer and interacts with various molecular partners." (PMID 40959108, 2025). "EZH2 can regulate CDH1 gene expression to affect EMT process of prostate cancer cell." (PMID 40959108, 2025). "Overexpression of EZH2 has been reported in several human malignancies, leading to EZH2 dysfunction and the suppression of tumor suppressor gene expression in conditions such as prostate cancer, NK/T-cell lymphoma, and melanoma." (PMID 40659662, 2025).
prostate carcinoma (continued). "For instance, studies demonstrate that ZDHHC5 participates in modifying cancer stem-like properties through interaction with EZH2—a pathway previously observed in glioma stem cells that may share conserved mechanisms with prostate cancer." (PMID 41343534, 2025). "In this way, N-Myc cooperates with EZH2 to drive the NE phenotype in prostate cancer." (PMID 38391963, 2024). "To understand the efficacy of EZH2 catalytic inhibition across lineage subtypes of prostate cancer, we performed cell viability and tumor growth experiments upon treatment with tazemetostat in a diverse panel of advanced prostate cancer models." (PMID 38405800, 2024). "It will therefore be relevant to test in future studies if EZH2 inhibitors, which are currently in clinical development for prostate cancer, can be used to pharmacologically enhance the expression of these cell surface antigens and, therefore, increase tumor targeting." (PMID 38760413, 2024). "Moreover, it has been confirmed that SChLAP1 facilitates prostate cancer progression by interacting with EZH2 to mediate DNA methylation of various miRNAs on chromosome 5 with a DNMT3A-feedback loop." (PMID 38890707, 2024). "However, methylation at K735 site, mediated by SETD2, promotes EZH2 degradation, counteracting prostate cancer metastasis." (PMID 39769907, 2024). "Mechanistically, DPYSL5 promotes prostate cancer cell plasticity via EZH2-mediated PRC2 activation." (PMID 38238517, 2024). "The high expression of EZH2 is involved in the progression of prostate cancer." (PMID 39072246, 2024). "Let-7 is also reported to regulate EZH2 to modulate CSC signatures of prostate cancer." (PMID 37596700, 2023). "Also of interest were several genes associated with prostate cancer metastases including FOXA1, EZH2, SCHLAP1, CDH1, SOX4, SOX9, HOXB13, and TGFBR3." (PMID 38067373, 2023). "Indeed, in prostate cancer cells, EZH2 inhibitors can rescue the expression of endogenous retrovirus (LTR/ERV), which results in a “viral mimicry” state." (PMID 36900330, 2023). "Besides its histone methyltransferase activity, EZH2 acts as a transcriptional co-activator in gene regulation processes involved in aggressive castration-resistant prostate cancer and in breast cancer." (PMID 36849558, 2023). "They treated the prostate cancer cells with triptolide and found that triptolide significantly inhibited the proliferation of prostate cancer and was also able to reduce enhancer of zeste homolog 2 (EZH2) expression." (PMID 37179342, 2023). "The role of EZH2 as an oncogenic driver is clear in prostate cancer." (PMID 37484909, 2023). "In prostate cancer, mutations of KMT2 genes (also known as mixed lineage leukemia family methylates) and dysregulation of EZH2 (enhancer of zeste 2 polycomb repressive complex 2 subunit) and LSD1 (lysine-specific demethylase 1, also known as KDM1A) are commonly observed and further enriched in CRPC." (PMID 37663929, 2023). "Additionally, the involvement of enhancer zeste homolog 2 (EZH2) in the metabolic process of prostate cancer through the miR-181b/HK II axis has been described." (PMID 38202657, 2023). "SETD2 promotes the degradation of EZH2 by methylating the EZH2 K735 site, preventing transformation of cells to a high H3K27me3 chromatin state, thereby inhibiting the molecular mechanism of prostate cancer metastasis." (PMID 37359376, 2023). "However, in animal and cell culture models of prostate cancer, EZH2 inhibitors modestly reduce proliferation, but exhibit little efficacy as single agents." (PMID 37104245, 2023). "For example, EZH2 directly regulates CMYC expression via association with the estrogen receptor alpha (ERα) and β-catenin, and conversely, MYC binds the promoter of EZH2 and regulates its expression in prostate cancer cells and B cell lymphomas." (PMID 37664059, 2023).
prostate carcinoma (continued). "Increased levels of PTEN and downregulation of EZH2 might contribute to the indolent nature of the prostate phenotype in Inpp4b−/− males and in the prostate epithelium and early prostate cancer in men." (PMID 38001678, 2023). "Knockdown of INPP4B but not PTEN in human prostate cancer cell lines caused a decrease in EZH2 expression." (PMID 38001678, 2023). "However, it should be emphasized that EZH2 has PRC-independent activity in prostate cancer where EZH2 is phosphorylated to act as a transcriptional coactivator." (PMID 37484909, 2023). "Furthermore, metformin inhibited the progression of EZH2-high expression prostate cancer by activating the AMPK-FOXO3-SETD2 signaling axis." (PMID 37359376, 2023). "Loss of EZH2 can induce down-regulation of BRAC1 that in turn triggers reprogramming capability, resulting in significantly increased tumor sphere formation, Levels of ALDH, and express stem cells phenotype in prostate cancer cells." (PMID 36969009, 2023). "These distinct roles for EZH2 in promoting prostate cancer progression, metastasis, and AR independence raise the possibility that it could be a potential therapeutic target in advanced disease." (PMID 37104245, 2023). "Indeed, after BR-DIM (metabolite 3,3′–diindolylmethane) treatment of prostate cancer cells, let-7c is up-regulated and EZH2 is down-regulated, which hampers the self-renewal and clonogenic properties of prostate cancer cells." (PMID 36969009, 2023). "In preclinical prostate cancer mouse cell line models, the simultaneous elevation of Top2a and EZH2 results in hypersensitivity to combined treatment with etoposide, a Top2-targeting toxin, and inhibitors of EZH2." (PMID 36678591, 2023). "Finally, we assessed the expression of ATF3-regulated genes in tumors with low levels of EZH2 (bottom 10%) and tumors with high levels of EZH2 (top 10%), in these 3 prostate cancer datasets." (PMID 37104245, 2023). "A recent study explored inhibiting prostate cancer development by targeting EZH2." (PMID 36884182, 2023). "It will therefore be important to test in future studies if EZH2 inhibitors, which are currently in clinical development for prostate cancer, can be used to pharmacologically enhance the expression of these cell surface antigens and, therefore, increase tumor targeting." (PMID 38196594, 2023). "In prostate cancer, EZH2 functions both as an epigenetic writer and AR coregulator." (PMID 38001678, 2023). "Nevertheless, while EZH2 plays a causal role in driving prostate cancer progression and metastasis, EZH2 suppression alone is not sufficient to kill prostate cancer cells in vitro or in vivo." (PMID 37104245, 2023). "Evaluation of the gene expression data in 499 prostate cancer patients in the TCGA dataset showed that EZH2 expression positively correlates with INPP4B (r = 0.1368, p = 0.0022), while the correlation is negative with PTEN expression (Spearman r = −0.1718, p = 0.0001)." (PMID 38001678, 2023). "An early example where EZH2 functions as an activator is in androgen-dependent prostate cancer." (PMID 37664059, 2023). "In addition, EZH2 silencing in prostate cancer cell experiments inhibits glucose metabolism process." (PMID 37179372, 2023). "It has been reported that EZH2 recruits USP7 to stabilize EZH2 in prostate cancer cells." (PMID 35163710, 2022). "In breast and prostate cancers, EZH2 has a crucial role, which is confirmed by our findings." (PMID 35345511, 2022). "Furthermore, EZH2 can enhance prostate cancer metastasis via Twist upregulation and increasing N-cadherin levels." (PMID 35236381, 2022). "Sox2 and EZH2 also play a key role in prostate cancer stem cells (PCSCs)." (PMID 35342431, 2022). "Others have reported that EZH2 was correlated with poor clinical outcomes for prostate cancer." (PMID 36712863, 2022). "In prostate cancer, EZH2 has also been used as a molecular marker for poor prognosis." (PMID 35955891, 2022).
prostate carcinoma (continued). "Therefore, in addition to its role as an epigenetic modifier that modulates prostate cancer cistromes, EZH2 also acts through additional direct and indirect mechanisms to regulate AR-driven prostate cancer progression." (PMID 36212399, 2022). "It has been reported that USP7 deubiquitinates and stabilizes EZH2 in prostate cancer cells." (PMID 35418124, 2022). "It plays a role in Burkitt lymphoma and prostate cancer prevention by targeting c-myc, a transcription factor of EZH2, and is involved in nasopharyngeal carcinoma inhibition by mitigating cyclin D3, E2, CDK4, and CDK6 along with overexpression of the CDK inhibitors p14ARF and p21CIP1." (PMID 35087589, 2022). "In another recent study, the EZH2 inhibition could stimulate IFNs through the activation of dsRNA in prostate cancer." (PMID 35912007, 2022). "YY1 recruits EZH2 in prostate cancer cells to down-regulate miRNA-146a expression." (PMID 35236381, 2022). "The only exception is EZH2, for which involvement in interactomes with both, lncRNA and circRNA, was shown in five epithelial cancers—hepatocellular carcinoma, ovarian carcinoma, gastric cancer, laryngeal squamous cell carcinoma, and prostate cancer." (PMID 36362406, 2022). "Additionally, EZH2 downregulation was detected in prostate cancer, myeloma, melanoma, kidney cancer, and leukaemia cancers." (PMID 35659256, 2022). "EZH2 also promotes tumor progression in pancreatic and prostate cancers." (PMID 36471782, 2022). "Thus, EZH2 is an important player in prostate cancer initiation, progression, and therapeutic response, owing partially to its role in modulating the epigenomic landscape and ensuing tumor transcriptome via its catalytic methyltransferase function." (PMID 36212399, 2022). "Furthermore, it has been reported that EZH2 can directly bind to USP7 in prostate cancer cells to stabilize EZH2, thereby promoting metastasis." (PMID 35163710, 2022). "Additionally, inhibition of EZH2 has been demonstrated to retard cell growth and glycolysis in prostate cancer." (PMID 35414117, 2022). "Consistent with this hypothesis, both genetic and chemical inhibition of EZH2 in prostate cancer organoids repressed the H3K27me3 levels and upregulated the endogenous dsRNA levels." (PMID 34737746, 2021). "Furthermore, SChLAP1 overexpression inhibited miR-340-5p/miR-143-3p/miR-145-5p expression in prostate cancer cells, which were abrogated by treatments with EZH2, H3K27me3, and DNMT3a inhibitors." (PMID 33589600, 2021). "For further exploration of the possible involvements of EZH2 and DNMT3a in regulating miR-340-5p, miR-145-5p, and miR-143-3p expression, we next inhibited EZH2 and DNMT3a activity in prostate cancer cells using specific inhibitors and gene knockdown technology." (PMID 33589600, 2021). "A recent study revealed that lincRNA-p21 could enhance EZH2-pS21 through inhibiting the EZH2-HOTAIR interaction, leading to PRC2 disruption in prostate cancer cells 123, indicating that lincRNA-p21 determines the outcomes of EZH2-mediated gene expression." (PMID 34512145, 2021). "Interestingly, our data displayed significant enrichment of a gene set regulated in prostate cancer cell after siRNA-mediated depletion of EZH2." (PMID 33803922, 2021). "Ili-A decreased EZH2 protein levels in prostate cancer cells via accelerated degradation of EZH2." (PMID 34776951, 2021). "Unlike prostate cancer, the principal EZH2 gene abnormalities in the GCB-DLBCL are missense mutations." (PMID 34202528, 2021). "In prostate cancer, EZH2 activates AR gene transcription through direct occupancy at its promoter." (PMID 34776951, 2021).